MYSM1 (Myb like, SWIRM and MPN domains 1)
Diseases named in the same sentence as MYSM1 in open-access papers (continued):
Sharing a sentence is not in itself a finding about the gene and the disease.
tumor (continued). "Consistently, IHC staining for p-Akt, constitutively activated in CRPC cells, showed that downregulation of MYSM1 resulted in a significant increase in p-Akt expression in tumor tissues derived from mice implanted with 22Rv1/shMYSM1 cells." (PMID 31761786, 2019). "We revealed the decreased expression of MYSM1 and confirmed its tumor-suppressing functions in CRPC." (PMID 31761786, 2019). "Significant intron retention was visible in MYSM1, the gene encoding for a metalloprotease, and WDFY1, a gene of WD repeat and FYVE domain‐containing protein, which plays an important role in tumour development." (PMID 39212334, 2025). "In addition, MYSM1 was negatively associated with the CRC stage (≤ IIIB or ≥ IIIC, P = 0.032) and the tumor stage (≤ T3 or T4, P = 0.026)." (PMID 34706761, 2021). "Importantly, in a mouse model of tumor metastasis, there were smaller and fewer metastatic nodules in the lungs of mice treated with Lenti-MYSM1-infected SW620 cells than in those of mice treated with Lenti-NC-infected SW620 cells." (PMID 34706761, 2021). "In addition, tumor weights of 22Rv1 xenografts in immunodeficient mice were significantly increased by downregulating MYSM1 levels." (PMID 31761786, 2019). "Moreover, we observed that the inhibition of MYSM1 significantly affected tumor growth in nude mice." (PMID 31761786, 2019). "It has been reported that some tumor-related genes were modulated by MYSM1." (PMID 28498834, 2017). "In addition, MYSM1 was expressed in tumor-infiltrating immune cells in the dermis in most SSM samples analyzed." (PMID 28978033, 2017). "In addition, increased A375 tumor cell apoptosis upon knockdown of MYSM1 was detectable by Annexin V staining (black bars)." (PMID 28978033, 2017). "In addition, the SSM samples analyzed showed significant co-localization of MYSM1 with tyrosine kinase c-MET in tumor cell clusters." (PMID 28978033, 2017). "In addition, association analyses by Pearson’s chi-square test verified that MYSM1 in tumors was positively correlated with tumor status and clinical stage." (PMID 28498834, 2017). "We next determined the expression levels of MYSM1 in 41 CRC patient samples, including paired samples of the adjacent normal mucosa (N), primary tumor tissue (T) and metastatic lymph node or hepatic tumor (M) tissue." (PMID 34706761, 2021). "Furthermore, MYSM1 downregulation in CRPC promotes cell proliferation and helps tumor cells, evading senescence under androgen ablation." (PMID 39684760, 2024). "Taken together, these data confirm that MYSM1 is negatively correlated with CRC development and indicate that it may serve as a tumor suppressor in vivo." (PMID 34706761, 2021). "Therefore, the potential role of the MYSM1-RFC-HELLS interaction in DNA repair and genome integrity will now need to be verified in tumor samples at different tumor stages and in response to treatment." (PMID 32466590, 2020). "Collectively, these data indicate that MYSM1 expression in CRPC cells results in the suppression of androgen-independent growth and induction of cell cycle arrest as well as cellular senescence, suggesting a tumor-suppressive role of MYSM1 in CRPC cells." (PMID 31761786, 2019). "Given the roles of MYSM1 and other histone modifiers in promotion of transcription, cellular growth, and transformation, it seems likely that functions of 2A-DUB/MYSM1 are essential in a number of tumor types." (PMID 28978033, 2017). "In this regard, the in vitro and in vivo studies indicate that the expression level of MYSM1 in primary tumor tissues is lower than that in adjacent normal tissues and is positively correlated with the OS of CRC patients, demonstrating the negative regulatory interaction between MYSM1 and CRC." (PMID 34706761, 2021).
tumor (continued). "In the future, better understanding of the functions of MYSM1 and its newly-identified interaction partners in DDR may lead to the identification of additional druggable targets sensitizing certain tumor cells towards DNA-damaging agents or radiation, as per the concept of synthetic lethality." (PMID 32466590, 2020). "The deubiquitination of histone H2A on lysine 119 by 2A-DUB/MYSM1, BAP1, USP16, and other enzymes is required for key cellular processes, including transcriptional activation, apoptosis, and cell cycle control, during normal hematopoiesis and tissue development, and in tumor cells." (PMID 32466590, 2020). "To further determine the anti-tumor role of MYSM1 in CRPC growth in vivo, we subcutaneously engrafted nude mice with 22Rv1 cells stably expressing shRNA targeting either MYSM1 or negative control and tracked tumor growth." (PMID 31761786, 2019).
cancer (11 papers, 2015 to 2025). A tumor composed of atypical neoplastic, often pleomorphic cells that invade other tissues. "Although the association between MYSM1 and cancer remains obscure, some clues indicate that MYSM1 is involved in tumorigenesis." (PMID 34706761, 2021). "Despite the repressive function of MYSM1 in cancer progression, our findings unveiled distinct molecular mechanisms underlying MYSM1-mediated cell growth inhibition in CRPC." (PMID 31761786, 2019). "In addition to its role in development, MYSM1 is closely associated with tumorigenesis across various cancer types." (PMID 39684760, 2024). "Besides, cell growth curves and colony formation proved that MYSM1 depletion made cancer cells more susceptible to the drug toxicity effects under the condition of higher dosage of specific endocrine drugs (G and EV5C)." (PMID 38177530, 2024). "No malignancies have been reported to date in MYSM1-deficiency syndrome in human, however, due to the low patient numbers and their young age, our understanding of cancer susceptibility in human MYSM1-deficiency may be incomplete." (PMID 32344625, 2020). "However, the limited sample size and young age of the patients suggest that our comprehension of the cancer susceptibility associated with Mysm1 deficiency in humans may be incomplete." (PMID 39684760, 2024). "Although the mechanisms underlying MYSM1’s role in tumorigenesis remain limited, these studies suggest that MYSM1 expression is crucial for assessing a clinical prognosis and may serve as a prognostic biomarker and therapeutic target for various cancers." (PMID 39684760, 2024). "Consistent with the previous observations, the immunoreactivity scores of MYSM1 in the carcinomas were found to be significantly lower than those in the adjacent normal tissues, and MYSM1 expression was inversely related to the CRC stage." (PMID 34706761, 2021). "In another tissue microarray of 100 carcinomas (T), including 80 samples harboring paired adjacent normal tissues (N), we detected the survival potential represented by MYSM1 expression." (PMID 34706761, 2021). "Several other studies also suggested a role for MYSM1 as a positive regulator of cancer progression." (PMID 32344625, 2020). "Several recent studies explored the role of MYSM1 in various cancer models and suggested both pro- and anti-carcinogenic functions of MYSM1 protein." (PMID 32344625, 2020). "To explore the expression of MYSM1 in human tumors, we performed web-based data mining to analyze The Cancer Genome Atlas (TCGA) datasets via GEPIA bioinformatics." (PMID 31761786, 2019). "The results showed that MYSM1 (P<0.001)was significantly highly expressed in primary carcinoma tissues (protein level:moderate) compared with normal mucosa tissues(protein level: weak)." (PMID 28498834, 2017). "The results showed that MYSM1 was significantly highly expressed in carcinoma tissues compared with adjacent normal mucosa tissues (P<0.05)." (PMID 28498834, 2017). "Protein levels of MYSM1 in normal mucosa (n = 30) and primary carcinoma (n = 30) tissues from CRC patients were detected by immunohistochemical staining." (PMID 28498834, 2017). "MYSM1 deficiency can also put patients at risk of other secondary cancers that are not related to the hematological system." (PMID 40535318, 2025). "Notably, in TNBC, the restoration of MYSM1 increases cisplatin-induced apoptosis, highlighting its various roles in cancer progression and treatment." (PMID 39684760, 2024). "In addition to clinical correlation between MYSM1 and cancer progression, our data show that ablating MYSM1 in CRPC cells robustly promotes cell growth and suppresses cellular senescence." (PMID 31761786, 2019). "Comparison between protein level of MYSM1 in primary carcinoma (n = 38) and that in liver metastasis tissues (n = 38) showed that MYSM1 (P = 0.001) was significantly increased in liver metastasis tissues (protein level: strong) compared with primary carcinoma tissues." (PMID 28498834, 2017).
cancer (continued). "MYSM1, as a member of H2A deubiquitinase family, might play a similar role in cancer progression." (PMID 28498834, 2017). "Therefore, we speculated that MYSM1 might play an important role in cancer progression and development." (PMID 28498834, 2017). "Here, I will focus on the emerging roles of the H2A DUBs USP3, USP16, USP44, BAP1, and MYSM1 in HSC maintenance and cancer." (PMID 26442100, 2015). "Collectively, our data presented here strongly support the role of MYSM1 in inhibiting tumorigenesis and suggest that MYSM1 may serve as a biomarker for CRC diagnosis and a promising target for cancer therapy." (PMID 34706761, 2021). "Interestingly, our current proteomics data now place MYSM1 in a functional network with PCNA, RFC, HELLS, and MCMBP with potential relevance in hematopoiesis and in cancer progression." (PMID 32466590, 2020). "Protein level of MYSM1 in primary carcinoma (n = 30) and lymphnode metastasis tissues (n = 30) detection indicated that MYSM1 protein expression in lymphnode metastasis tissues did not exhibit significant elevation relative to primary carcinoma groups (P = 0.136)." (PMID 28498834, 2017).
infection (5 papers, 2018 to 2026). The state of being infected such as from the introduction of a foreign agent such as serum, vaccine, antigenic substance or organism. "In an experimental cerebral malaria model, mice with an Mysm1 deficiency had a sustained decrease in CD8+ T cell numbers after infection, but showed improved survival rates after a parasitic challenge." (PMID 39684760, 2024). "The expression of MYSM1 in these cell lines was either suppressed by transient transfection with a pool of specific small interfering RNAs (siRNAs) or enhanced via infection with Lenti-MYSM1 particles." (PMID 34706761, 2021). "MYSM1 was also shown to have a direct role in the regulation of macrophage activation, in response to inflammatory stimuli and infection." (PMID 32344625, 2020). "The deubiquitinase MYSM1 is a key component of the epigenetic signaling machinery, but accumulates in the cytoplasm in response to infection or TLR signaling." (PMID 30405132, 2018). "Furthermore, MYSM1 directly influences macrophage activation in response to inflammatory stimuli and infections." (PMID 39684760, 2024). "Thus, a cytosolic pool of MYSM1 protein is produced transiently in mouse macrophages, in response to inflammatory stimulation or infection, involving de novo protein synthesis and subsequent proteasomal degradation." (PMID 32344625, 2020).
hematologic malignancies (2 papers, 2020 to 2023). "Overall, these studies may suggest MYSM1 as a drug-target for cMYC driven hematologic malignancies; and the Mysm1DN mouse strain described in our current work will allow to test whether the loss of MYSM1 DUB catalytic function can offer similar therapeutic benefits." (PMID 36611064, 2023). "This can serve as a proof-of-concept for the development of pharmacological MYSM1 inhibitors and for the assessment of their activities in experimental models of cMYC-driven hematologic malignancies." (PMID 36611064, 2023).
MYSM1 also shares sentences with these, for which no sentence is quoted: immune dysfunction (5 papers); inherited bone marrow failure syndrome (3); leukopenia (3); lung adenocarcinoma (2); ovarian serous cystadenocarcinoma (2); peritonitis (2); rectal adenocarcinoma (2); renal carcinoma (2); skin cutaneous melanoma (2); Thrombocytosis (2); thyroid carcinoma (2); uterine carcinosarcoma (2); adenocarcinoma (1); adrenocortical carcinoma (1); Anxiety (1); Autoimmunity (1); B cell deficiency (1); B cell lymphopenia (1); benign prostatic hyperplasia (1); cardiac hypertrophy (1); cervical squamous cell carcinoma (1); DiGeorge syndrome (1); endocervical adenocarcinoma (1); Fanconi anemia (1); genitourinary cancer (1); glioblastoma (1); glioma (1); Glomerular sclerosis (1); graft versus host disease (1); hepatic veno-occlusive disease (1).
A further 21 diseases each share a sentence with MYSM1 in 1 paper.